TLR4 (toll like receptor 4)
Diseases named in the same sentence as TLR4 in open-access papers (continued):
Sharing a sentence is not in itself a finding about the gene and the disease.
Cerebral ischemia (continued). "It is widely demonstrated that TLR4 is involved in brain damage and the knock-out of TLR4 has neuroprotective effects against cerebral ischemia–reperfusion injury." (PMID 32265630, 2020). "Recent studies showed that inhibition of Cx43 hemichannels alleviated cerebral ischemia via the toll-like receptor (TLR4) or JAK2/STAT3 pathway." (PMID 32982919, 2020). "TAK-242 is a specific antagonist of TLR4, which is able to block TLR4 signaling, mediates the expression of inflammatory cytokines, and protects the brain from damage due to cerebral ischemia." (PMID 32850002, 2020). "The expression levels of TLR4 and NF-κB in ischemic brain tissue increased at 24 h after cerebral ischemia, but SSa significantly downregulated the expression of TLR4 and NF-κB as indicated by the Western blot analysis." (PMID 33335763, 2020). "Recent findings pointed out a protective activity of cyanidin-3-O-glucoside in a mouse model of brain ischemia through the modulation of TLR4, NF-κB, Nrf2 and NLPR3." (PMID 33383852, 2020). "It has also been reported that brain ischemia induces TLR4 expressions in astrocytes, and that TLR4 activation leads to an astroglial polarization towards an inflammatory phenotype." (PMID 32248810, 2020). "Pretreatment with dexmedetomidine exerted neuroprotective effects in a model of cerebral ischemia-reperfusion by inhibiting the TLR4/NF-κB pathway and reducing inflammatory damage." (PMID 31682592, 2019). "DEX can also regulate MAPK and TLR4 signals to reduce the inflammatory response and oxidative stress during cerebral ischemia-reperfusion injury, which also alleviate renal ischemia-reperfusion injury in rats." (PMID 31886285, 2019). "After cerebral ischemia-reperfusion injury, TLR4 expression is increased, resulting in a decrease in IκB expression, the activation of NFκB and microglia, and the increased expression of related proapoptotic proteins." (PMID 30723536, 2019). "TLR4 plays an important role in cerebral ischemia-reperfusion injury; TLR4 expression was increased in cerebral cortical neurons in response to ischemia/reperfusion injury." (PMID 30723536, 2019). "PolyI:C also shows therapeutic effect against cerebral ischemia/reperfusion injury through the downregulation of TLR4 signaling." (PMID 31130960, 2019). "Our study demonstrated the meisoindigo had neuroprotective effects on cerebral ischemia through decreasing NLRP3 inflammasome components expression via inhibition of activation of the TLR4/NF-κB pathways." (PMID 31920554, 2019). "Isoflurane preconditioning was found to reduce microglial activation and the inflammatory response through the TLR4/NFκB signaling pathway in a cerebral ischemia-reperfusion injury model and to reduce brain injury." (PMID 30723536, 2019). "Toll-like receptor 4 (TLR4) plays a key role in cerebral ischemia and reperfusion injury by inducing the production of inflammatory mediators, such as interleukins (ILs) and tumor necrosis factor-alpha (TNF-α)." (PMID 29867706, 2018). "UA was initially described that modulated potentially of HMGB1/TLR4/NFκB-mediated inflammation and ameliorated cerebral ischemia and reperfusion injury in the present study." (PMID 29867706, 2018). "Our results are the first to demonstrate that specific blocker of Cx43 hemichannels-Gap19 plays a vital role in protecting cerebral ischemia via inhibition of activation of the TLR4 pathways." (PMID 30386214, 2018). "The activation of TLR-4 activates NF-κB during cerebral ischemia, and NF-κB further promotes the production of NLRP3 and IL-1β— thus, enhancing inflammation." (PMID 30618576, 2018). "The TLR4-mediated inflammatory response plays a crucial role in cerebral ischemia-reperfusion injury." (PMID 29113305, 2017). "Cerebral ischemia significantly activated the TLR4/NF-kB signaling pathway, reflected by increases in the expression of TLR4 and nuclear translocation of NF-kB p65 in the MCAO group compared with sham controls (p < 0.01)." (PMID 29207618, 2017).
Cerebral ischemia (continued). "Toll-like receptor 4 (TLR4) is an important mediator of the neuroinflammatory response to cerebral ischemia/reperfusion injury." (PMID 29113305, 2017). "TLR-2- and TLR-4-knockout mice showed less brain damage and neuronal deficits after 3 days of cerebral ischemia induced by MCAO." (PMID 29054968, 2017). "Due to a recent report on the detrimental effects of TLR2-deficiency after experimental ischemia in the long-term, we evaluated if the potential detrimental effects of TLR4-inhibiton occur up to 14d after induction of cerebral ischemia." (PMID 26849209, 2016). "Similar to TLR2, TLR4 is also significantly upregulated in microglia and astrocytes 24 h after cerebral ischemia." (PMID 28101118, 2016). "Emerging clinical and experimental studies have highlighted the key roles of TLR2 and TLR4 in microglia, which contribute to inflammatory responses occurring after cerebral ischemia-reperfusion injuries." (PMID 28101118, 2016). "Studies of TLR4 knockout mice showed smaller infarct sizes and improved neurological deficits after cerebral ischemia." (PMID 27716839, 2016). "Increased Prx6 was reported to be the major danger associated molecular patterns (DAMPs) that induce infiltrating macrophage activation and the subsequent production of cytokines from invading T cells after cerebral ischemia through TLR4 signal pathway." (PMID 26681963, 2015). "Puerarin has been reported to inhibit TLR4 innate signaling pathway in cerebral ischemia/reperfusion-induced tissue." (PMID 26576421, 2015). "A recent study identified extracellular Prx5 and Prx6 as major TLR2/TLR4-dependent DAMPs in aseptic inflammation after cerebral ischemia." (PMID 26681963, 2015). "In this study, we observed the activation of cerebral ischemia induced TLR4 signaling, including enhancing the protein expression of Prx6 and TLR4, and the activation of MAPK signal pathway." (PMID 26681963, 2015). "Following cerebral ischemia, the activation of TLR4 by HMGB-1 induces MMP-9 up-regulation in neurons and astrocytes and promotes detrimental effects by macrophages infiltrating the injured brain." (PMID 25972779, 2015). "Several studies using TLR knockout mice, usually TLR4, demonstrate detrimental effects of TLRs in cerebral ischemia." (PMID 26597908, 2015). "Subsequently, the whole cerebral ischemia model further confirmed that the cerebral ischemic damage in TLR4-knockout mice was also significantly reduced." (PMID 25928750, 2015). "For example, the application of LPS (a powerful TLR4 agonist) as preconditioning prior to cerebral ischemia reduced the subsequent cerebral ischemic injury and improved the neurological function score, which was termed LPS tolerance." (PMID 25928750, 2015). "Cerebral ischemia significantly induced the subsequent activation of TLR4 signaling effectors, reflected by increasing the phosphorylation levels of p38, ERK, and JNK in the ischemic brain in model group compared with control groups." (PMID 26681963, 2015). "In the focal MCAO model, the protective effect of LPS preconditioning against cerebral ischemia was dependent on the TLR4 signal transduction via TRIF." (PMID 25928750, 2015). "TLR4 activation is also known to upregulate NOX4 after rodent cerebral ischemia leading to the production of ROS." (PMID 26030867, 2015). "EDA-mediated TLR4 signaling is thought to contribute to adverse inflammation following cardiac infarction, cerebral ischemia, allergen challenge, graft vs. host disease, and pre-term birth." (PMID 25051083, 2014). "The level of TLR4 mRNA increased in neurons after 1 h of cerebral ischemia, which was accompanied by the high level of multiple inflammatory cytokines." (PMID 23864765, 2013). "Toll-like receptor 2 (TLR2) and Toll-like receptor 4 (TLR4) are considered to mediate the inflammatory reaction of cerebral ischemia injury, and exercise can inhibit the activity of the Toll-like receptor signaling pathway in the peripheral blood of humans." (PMID 23434667, 2013).
Cerebral ischemia (continued). "In particular, TLR2 and TLR4 were found to be more important than other TLRs in the pathologic progression of cerebral ischemia and reperfusion." (PMID 23864765, 2013). "There is a definite conclusion on the basis of current findings that TLR2 and TLR4 exert key influences on the pathological process of cerebral ischemia/reperfusion." (PMID 23864765, 2013). "The mice pretreated at 72 h prior to cerebral ischemia and reperfusion with subcutaneous injection of low dose of LPS, a specific ligand of TLR4, showed decreased brain infarction." (PMID 23864765, 2013). "Although the central nervous system is a sterile circumstance and no pathogens such as germs or viruses exist under normal or ischemic condition, it is found that cerebral ischemia causes elevation in the expression of TLR2, TLR4, and TLR9 in neurons." (PMID 23864765, 2013). "Toll-like receptor 4 (TLR4) is activated in response to cerebral ischemia leading to substantial brain damage." (PMID 21999375, 2011). "In contrast, mild activation of TLR4 by preconditioning with low dose exposure to lipopolysaccharide (LPS) prior to cerebral ischemia dramatically improves outcome by reprogramming the signaling response to injury." (PMID 21999375, 2011). "There are several studies exploring endogenous ligands that activate TLR-4 after brain damage (e.g. protein S100 or nuclear protein high-mobility group box 1 after cerebral ischemia, pro-inflammatory cytokines after brain trauma)." (PMID 22053929, 2011). "Several studies confirm that cerebral ischemia results in the upregulation of TLR4 mRNA in neurons as early as one hour after initiation of ischemia in vivo." (PMID 21982558, 2011). "TLR4-induced tolerance to cerebral ischemia was first demonstrated with low-dose systemic administration of LPS, which rendered spontaneously hypertensive rats tolerant to ischemic brain damage induced by MCAO." (PMID 21982558, 2011). "In a later study, the same authors used knockout mice to show differential roles for TLR2 and TLR4 in cerebral ischemia." (PMID 20628516, 2010). "It has been found that cerebral ischemia/reperfusion injury activates the HMGB1/TLR4 axis by inhibiting the expression of glutamate transporter (GLAST) in primary astrocytes, thereby decreasing glutamate clearance activity and increasing excitatory amino acid-mediated ischemic injury." (PMID 38740617, 2025). "Additionally, DEX has the capacity to reverse neuronal apoptosis and autophagy, thereby playing a neuroprotective role in the cerebral Ischemia/Reperfusion (I/R) model by antagonizing the Toll-Like Receptor 4 (TLR4) signaling pathway." (PMID 40949160, 2025). "Their findings revealed that lamprophyllin could protect against cerebral ischemia–reperfusion injury by regulating intestinal microbiota, inhibiting TLR4/MyD88/NF-κB inflammatory pathways in the brain, and regulating intestinal CYP3A4 expression." (PMID 40308697, 2025). "In line with our findings, previous reports indicate that miR-21 attenuates inflammatory responses in retinal I/R through PDCD4 or TLR4-dependent mechanisms, and in brain ischemia fosters M2 polarization of microglia with concomitant neuroprotection by engaging the PI3K/AKT signaling axis." (PMID 41153739, 2025). "Previous studies align with our findings, indicating that glycyrrhizin modulates inflammation, oxidative stress, and related processes via the HMGB1/TLR4/NF-κB signaling pathway, benefiting neurological disorders such as cerebral ischemia, cognitive impairment, and neurotoxicity." (PMID 39834818, 2024). "Calycosin might alleviate cerebral ischemia-reperfusion injury by inhibiting the HMGB1/TLR4/NF-κB pathway." (PMID 37528661, 2023). "Many studies have revealed that the inflammatory response plays a key role in the pathophysiology of cerebral ischaemia‒reperfusion injury, and the activation of the HMGB1/TLR4/NF-κB signaling pathway has been found to be involved in cerebral ischemia-induced inflammation." (PMID 37528661, 2023).
Cerebral ischemia (continued). "Toll-like receptor 4, as one of the most researched TLRs, was significantly activated after cerebral ischemia, and the inhibition of TLR4 could effectively reduce inflammation following ischemic stroke." (PMID 38273974, 2023). "Thus, much effort is still required to fully elucidate the role of TLR4 in inducing inflammation and autophagy in cerebral ischemia/reperfusion injury." (PMID 36879557, 2023). "In addition, we investigated the anti‐inflammatory properties of Sal B. Following cerebral ischemia, we found that Sal B significantly reduced TLR4, p‐p38MAPK, p‐JNK, IL‐1β expression, and nuclear translocation of NF‐κB." (PMID 37904689, 2023). "Analgecine (AGC), an analgesic for lumbar pain in patients with spinal degenerative diseases, has been shown to inhibit M1-type polarization and promote M2-type polarization by inhibiting TLR4/MyD88/NF-κB signaling pathway, which reduced neuroinflammation during cerebral ischemia." (PMID 37361996, 2023). "Among them, TLR4 participates in the progression of cerebral ischemia and reperfusion." (PMID 36619717, 2022). "We hypothesized that miRNA-loaded extracellular vesicles would mitigate TLR4 in our hiPSC-EC model, as miR-451a has been shown to decrease the mRNA levels of TLR4 in murine cerebral ischemia models." (PMID 36618355, 2022). "Meanwhile, polydatin treatment downregulated the expression of cerebral ischemia or spinal cord injury (SCI)-induced inflammatory mediators such as Toll-like receptor 4 (TLR4), NF-κB, cyclooxygenase-2 (COX-2), inducible nitric oxide synthase (iNOS), nitric oxide (NO), and ICAM-1." (PMID 36235012, 2022). "Notably, gap19 inhibited the activation of the TLR4 (Toll-like receptor 4) pathway, a well-known mechanism for secondary injury after cerebral ischemia." (PMID 36140338, 2022). "Previously, it has also been shown that TLR4 could lead to inflammatory injuries in the central nervous system during cerebral ischemia and infection." (PMID 35170388, 2022). "Studies have shown that under the condition of cerebral ischemia or cerebral ischemia‐reperfusion, TLR4 gene‐knockout mice had significantly reduced infarct areas and volumes, decreased activation of NF‐κB and expression of inflammatory factors and related mediators, compared with wild‐type mice." (PMID 33704926, 2021). "Moreover, high-mobility group box 1 (HMGB1) is released resulting in TLR4-dependent MMP-9 upregulation in the brain following cerebral ischemia in mice." (PMID 33487119, 2021). "Garcinol reduces cerebral ischemia-reperfusion injury by downregulating TLR4-NFκB." (PMID 35008558, 2021). "The study suggests that naltrexone and other TLR4 antagonists could strategically improve memory and executive function after cerebral ischemia in the hippocampus." (PMID 34206997, 2021). "Furthermore, HMGB1 has been shown to activate TLR4 to induce MMP-9 upregulation following cerebral ischemia." (PMID 33487119, 2021). "Similarly, Kudiezi injection improves the cerebral ischemia-reperfusion injury of rats by downregulating the TLR4-NFκB pathway." (PMID 35008558, 2021). "Increasing evidence indicates that TLR4 activation leads to oxidative stress after brain ischemia." (PMID 34836132, 2021). "Our previous studies found that inhibiting the expression of TLR4 and NF-κB significantly alleviates cerebral ischemia injury, and another recent study verified that suppression of the TLR4/NF-κB signaling pathway improved cerebral ischemia-reperfusion injury in rats." (PMID 32917229, 2020). "The synergies of cerebral ischemic damage with air pollution, observed clinically and in a rodent model, may now be understood as mediated by the nPM-LPS TLR4 modules described here and the TLR4 role in cerebral ischemia." (PMID 28410596, 2017). "Thus, our studies are the first to show that vinpocetine also exerts an anti-inflammatory effect by inhibiting the TLR4/MyD88/NF-κB signaling pathway in a cerebral ischemia and reperfusion model." (PMID 29113305, 2017).
Cerebral ischemia (continued). "However, in the context of cerebral ischemia, the effect of TLR4 activation by endogenous ligands on the regeneration of nerve cells and tissue repair awaits further study." (PMID 25928750, 2015). "Interestingly, ischemic preconditioning induced by 6 min of blockade in the bilateral carotid artery had a protective effect on the cerebral ischemia of wild-type mice; however, this protective effect disappeared in TLR4-/- mice." (PMID 25928750, 2015). "Notably, a significantly reduced area of cerebral infarction and an alleviation of inflammatory responses in the brain have been observed in TLR4 knockout mice following cerebral ischemia." (PMID 25187844, 2014). "Under cerebral ischemia and anoxia, the activated TLR4 promotes the expression of nuclear factor (NF)-κB and induces the production of cytokines, such as tumor necrosis factor (TNF)-α and interleukin (IL)-6, thereby causing inflammation and neurological injury." (PMID 25187844, 2014). "However, although TLR4 participates in both cerebral ischemia- and ICH-induced brain injuries, the signaling pathways involved are different." (PMID 23414417, 2013). "Therefore, by considering the critical role of TLR4 in the neuroinflammation and cerebral ischemia, the present study aims to establish the potential role of TLR4 in the TBI." (PMID 23555560, 2013). "Moreover, other means have also been exerted to suppress overexpression of TLR2 and TLR4 during cerebral ischemia/reperfusion." (PMID 23864765, 2013). "However, studies have demonstrated that TLR2 and TLR4 appear to play opposing roles in cerebral ischemia." (PMID 21982558, 2011). "This would suggest that TLR4 signaling plays a significant and detrimental role in brain ischemia." (PMID 21385378, 2011). "TLR2 and TLR4 both appear to play critical but opposing roles in cerebral ischemia." (PMID 20628516, 2010). "Interestingly, we have also demonstrated the deleterious role of platelet TLR4 in brain ischemia caused by non-platelet-rich thrombosis." (PMID 35250974, 2022). "Given that inflammation is a crucial factor in secondary injury after brain ischemia and that TLR4 plays a pivotal role in the inflammatory response in the ischemic brain, the TLR4-dependent pathway may be involved in the possible neuroprotective effects of propofol against ischemic brain injury." (PMID 36117859, 2022). "In addition to lipopolysaccharide (LPS), which is a well-known ligand of TLR4, damaged mitochondria are also a natural ligand of LPS, suggesting that mitochondrial fragments generated during the early events of cerebral ischemia in turn act as ligands for TLR4 and induce secondary inflammation." (PMID 34207355, 2021). "Therefore, strategies that modulate post-ischemic TLR4 signaling in the brain may suppress inflammation induced by cerebral ischemia and provide new therapies for stroke." (PMID 29867706, 2018). "Thus, we hypothesized that vinpocetine may alleviate cerebral ischemia and reperfusion injury by down-regulating TLR4/MyD88/NF-κB signaling." (PMID 29113305, 2017). "Moreover, neurons express TLR2 and TLR4 1 h after cerebral ischemia-reperfusion injuries." (PMID 28101118, 2016). "In addition, NOX4 was co-immunoprecipitated with TLR4 after cerebral ischemia in mice." (PMID 26030867, 2015). "Additionally, after adding the serum of patients with cerebral ischemia into the cultured monocytes and human umbilical vein endothelial cells, a strong inflammatory response occurred, which was blocked by the addition of a TLR4 antibody." (PMID 25928750, 2015). "However, our study is unique in that we attempted to ascertain the roles of different signaling pathways downstream of TLR4 activation and followed the mice out to 15 days to better parallel the human condition where delayed cerebral ischemia can occur up to 21 days from ictus." (PMID 23849248, 2013).